AQP5-AS1 (AQP5 and AQP2 antisense RNA 2)
Description:
Reduces filamentous actin fibers by interacting with aquaporin AQP2 which leads to inhibition of the expression of SEPTIN4 and integrin ITGB4. Also inhibits the activation of the EREG/EGFR signaling pathway through interaction with AQP2.
Synonyms: MIAC; AC025154.2
Gene: Long non-coding RNA gene on chromosome 12 (49,951,512 to 49,975,539, reverse strand). Ensembl gene ENSG00000257588.
Diseases named in the same sentence as AQP5-AS1 in open-access papers:
AQP5-AS1 is named in the same sentence as 10 diseases in open-access papers, as found by Europe PMC text mining. Sharing a sentence is not in itself a finding about the gene and the disease.
AQP5-AS1 shares sentences with these, for which no sentence is quoted: renal carcinoma (3 papers); tumor (3); cancer (1); colon adenocarcinoma (1); head and neck squamous cell carcinoma (1); kidney cancer (1); lung adenocarcinoma (1); prostate carcinoma (1); renal cell carcinoma (1); thyroid cancer (1).